MGMT (O-6-methylguanine-DNA methyltransferase)
Diseases named in the same sentence as MGMT in open-access papers (continued):
Sharing a sentence is not in itself a finding about the gene and the disease.
glioma (continued). "These scholarly achievements not only serve as a benchmark for the dissemination of related research, but they also provide a theoretical framework for future translational application of MGMT methylation modulation in clinical glioma treatment." (PMID 39286478, 2024). "In the work-up of any adult-onset glioma, MGMT promoter methylation testing is a frequent theranostic adjunct." (PMID 38791984, 2024). "Here we present an experimental approach based on recent advancements in epigenetic editing, namely CRISPRoff, to enable the study of the impact of different MGMT promoter region methylation patterns in isogenic glioma cell lines." (PMID 38357209, 2024). "It is well-known that gliomas can be molecularly characterised considering several epigenetic markers, such as changes in the promoter methylation pattern of MGMT and hTERT genes." (PMID 37239035, 2023). "Using The Cancer Genome Atlas (TCGA), we found that ASAH1 was elevated in MGMT unmethylated gliomas, but the other ceramidases were unchanged." (PMID 38086808, 2023). "This combination incorporates immune and metabolic factors, not only accurately predicting the prognosis, but also distinguishing different glioma molecular subtypes, including IDH1 mutation, MGMT promoter methylation, and 1p/19q co-deletion." (PMID 37891828, 2023). "Low-intensity fluorescence ultrasound (LIFU) was employed to deliver a liposomal O6-(4-bromothenyl) guanine (O6BTG) derivative that inactivates MGMT in a mouse model with temozolomide-resistant glioma." (PMID 38137175, 2023). "Several prospective studies have examined subsets of CpGs of MGMT in high-grade gliomas, however, to date only few have systematically investigated a large number or even all CpG sites of the MGMT CpG-island." (PMID 37641156, 2023). "TMZ is a first-line treatment for glioma, and the MGMT promoter methylation status is a factor that predicts therapeutic responses to TMZ." (PMID 37889551, 2023). "In terms of well-known molecular markers, IDH mutation, 1p/19q codeletion, MGMT promotor methylation, wild-type TERT promoter, and ATRX mutation glioma samples correlated with lower infiltration of reactive astrocytes." (PMID 37416308, 2023). "While none of those exact cutoffs were statistically significant, there were clearly different slopes of MGMT promoter methylation positivity curves as a function of VAF within each glioma subtype (and 2 N)." (PMID 37919784, 2023). "Currently, there are several methods to predict glioma prognosis, including clinicopathological classification, MRI imaging, and molecular markers (such as IDH mutation status, 1p/19q codeletion, MGMT promoter methylation status, etc.)detection." (PMID 36861130, 2023). "Methylation at the O6-methylguanine-DNA methyltransferase (MGMT) gene promoter has been detected in nearly 50% of high-grade gliomas and is being used as a good prognostic marker for effective chemotherapy." (PMID 37947625, 2023). "Comparative analysis of the conventional methylation-specific PCR (MSP) vs. the quantitative MSP (qMSP) assessment of the O6-methylguanine-DNA methyltransferase (MGMT) promoter methylation status in 34 snap-frozen (SF) glioma samples was performed." (PMID 36766464, 2023). "The methylation of MGMT promoter is a vital reference factor for the clinical treatment of glioma patients, which indicates that glioma patients have a better therapeutic response to the first-line chemotherapy drug temozolomide." (PMID 37004060, 2023). "This study explored the application of radiomics based on preoperative MRI to establish a radiomic model for predicting the molecular subtype of IDH mut combined with MGMT meth in glioma." (PMID 36900232, 2023). "Brain MRI demonstrated a non-enhancing infiltrating mass in the left temporal lobe suspected to be a glioma (reported postoperatively by clinical pathology as WHO Grade 3 Anaplastic Astrocytoma with MGMT promoter methylation)." (PMID 36765783, 2023).
glioma (continued). "1p19q codeletion is a combination of loss of the short arm chromosome 1 (1p) and the long arm of chromosome 19 (19q), 1p19q codeletion, MGMT promoter methylation and/or IDH1 mutation signified a better prognosis for glioma patients." (PMID 37864127, 2023). "Conversely, MGMT promoter methylation is often used as an inclusion criterion for glioma trials involving TMZ-sensitizing strategies." (PMID 37919784, 2023). "The expression levels of SHOX2 were significantly associated with the grades and clinical features of glioma patients, such as IDH status, 1p/19q status, MGMT status and new types." (PMID 37170390, 2023). "Diffuse hemispheric glioma H3 G34-mutant is known to have a high rate of MGMT promoter hypermethylation compared to other pediatric diffuse gliomas." (PMID 37670377, 2023). "Given that both MGMT and NF-κB are strongly expressed in the TR/U251 glioma cell line, a link between them and TMZ resistance is likely." (PMID 36675073, 2023). "When glioma driver mutation VAF is low, MGMT promoter methylation scores by pyrosequencing also tend to be lower, and negative test results are more frequent." (PMID 37919784, 2023). "To better understand the relationship between the risk signature and clinical characteristics, we analyzed the distribution of survival status, WHO classification, risk scores, MGMT, and IDH status of glioma patients." (PMID 37698534, 2023). "Glioma patients with unmethylated MGMT promoters showed relatively higher levels of GA-MSCRGPI in the TCGA cohort, whereas other results were consistent with those in both CGGA cohorts." (PMID 37005685, 2023). "In conclusion, significant prognostic factors for survival in patients with IDH1-wt and MGMT-unmet high-grade gliomas were age and the extent of surgery." (PMID 38168519, 2023). "We found MGMT promotor unmethylated glioma (p = 0.0072), recurrent glioma (p = 0.041), or with TMZ chemotherapy (p = 0.037) patients had higher level of PVT1 expression." (PMID 37202742, 2023). "Ideally, research should have a narrow focus on more specific glioma types with a regard to their genetic and epigenetic characteristics, such as IDH1/2 gene mutations and MGMT methylation status." (PMID 37239035, 2023). "MGMT-methylated gliomas exhibit decreased DSC-CBV, whereas unmethylated gliomas show increased Ve and Ktrans." (PMID 36830900, 2023). "demonstrate a significant 6-month difference in survival between patients treated in the AM and PM, highlighting the role of the circadian system on TMZ sensitivity in MGMT-methylated gliomas." (PMID 38173841, 2023). "In conclusion, this study constructed a radiomics model for predicting the molecular subtype of IDH mut combined with MGMT meth in glioma via radiomics based on preoperative MRI." (PMID 36900232, 2023). "Hypermethylation of tumor suppressor genes is increasingly being explored as a prognostic marker in low-grade gliomas, for instance, testing for MGMT methylation status to predict response to chemotherapy." (PMID 36831683, 2023). "One pertinent example is the glioma CpG island methylator phenotype (G-CIMP), a pattern of genetic changes that includes MGMT methylation, which is often associated with the presence of IDH1 or IDH2 gene mutations." (PMID 36831683, 2023). "The expression of the LAG difference was also mapped to illustrate its relationship with the cluster model, IDH status, 1p19q status, MGMT methylation status, and glioma CpG island methylator phenotype (G-CIMP) status." (PMID 37122693, 2023). "Comparative analysis of two methods for the determination of MGMT marker in gliomas, MSP and qMSP, is performed." (PMID 36766464, 2023). "When pooled together, gliomas in which MGMT promoter methylation was determined by DNA methylation array using the Bady algorithm showed a VAF cutoff of 0.245." (PMID 37919784, 2023).
glioma (continued). "Complete 1p/19q co-deletion, MGMT promoter methylation and IDH1 mutation which are associated with favorable outcomes in gliomas were more obvious in the low-risk group as risk scores increased (all p < 0.001, Spearman correlation)." (PMID 38057821, 2023). "Total 226 patients with LM (from 2001 to 2021 among 1495 grade 2 to 4 glioma patients, 88.5% of LM patients being IDH-wildtype) with complete information on IDH mutation, 1p/19q codeletion, and MGMT promoter methylation status were enrolled." (PMID 36841906, 2023). "Among the three major glioma subtypes, similar positive correlations were found for MGMT promoter methylation and TERT promoter VAF in IDHwt GBM, and for IDH VAF in both IDHmut astrocytoma (non-significant) and IDHmut oligodendroglioma." (PMID 37919784, 2023). "Radiomics predictors were also built for genetic features implicated in prognosis such as MGMT methylation and EGFRA289V mutations in high grade gliomas, and ATRX mutations in LGGs." (PMID 36830900, 2023). "MGMT promoter methylation testing is required for prognosis and predicting temozolomide response in gliomas." (PMID 37919784, 2023). "The DNA methylation status of the MGMT promoter in gliomas was the first clinically used epigenetic biomarker and since that time much of the focus on glioma epigenetics has been on DNA methylation." (PMID 37528157, 2023). "The results of univariate Cox regression revealed that prognostic factors for gliomas include cluster, age, grade, classification, MGMT promoter status, chromosome 1p/19q codeletion status, and IDH mutation status." (PMID 38161335, 2023). "Mann-Whitney U tests based on regression cutoffs for glioma subtypes showed significant variation of median MGMT promoter methylation scores only for IDHmut oligodendroglioma (18.2% vs. 27.2%, p = 0.0003)." (PMID 37919784, 2023). "As a 1p/19q codeletion, MGMT promoter methylation and IDH1 mutation is an important marker for the prognostic evaluation of glioma patients, and we investigated expression of HIC2 and this clinicopathologic feature." (PMID 36650953, 2023). "Further, we aimed to compare the validity of SF and formalin-fixed paraffin-embedded (FFPE) glioma samples for MGMT testing." (PMID 36766464, 2023). "The mean methylation status of CpGs 72–83 of all glioma samples with the methylated MGMT promoter was 64.2%." (PMID 37371109, 2023). "O6-methylguanine DNA methyltransferase (MGMT) gene promoter methylation and IDH mutation status allow for the stratification into biologically and prognostically distinct subgroups of glioma patients, PsP being more frequent." (PMID 38201621, 2023). "Methylation of the MGMT promoter in gliomas predicts longer survival and better response to alkylating chemotherapy agents such as temozolomide, and is thus a clinically vital molecular feature to determine." (PMID 38161802, 2023). "Here, we show that glioma driver mutation VAF, which is included in most NGS reports, can serve as a useful metric for judging the reliability of MGMT promoter methylation pyrosequencing results, more so than microscopic cellularity estimates." (PMID 37919784, 2023). "Of note, grading largely informs the management approach at initial diagnosis and relapse, and MGMT methylation status is a vital prognosticator in an era where most gliomas are treated with alkylating agents." (PMID 37733174, 2023). "SHOX2 expression level was significantly correlated with isocitrate dehydrogenase (IDH), 1p/19q, O6-methylguanine DNA methyltransferase (MGMT) status and new types of glioma patients." (PMID 37170390, 2023). "Across all 92 glioma cases, microscopy along with immunohistochemistry and O6-methylguanine-DNA-methyltransferase (MGMT) pyrosequencing was sufficient for a final, integrative diagnosis in 45 cases (49% of the total glioma subset)." (PMID 37553446, 2023). "The DNA repair gene O6‐methylguanine‐DNA methyltransferase (MGMT) is the most prominent epigenetically silenced gene in glioma." (PMID 37786553, 2023).
glioma (continued). "MGMT codes for O-6-methylguanine DNA methyltransferase, a DNA repair protein that diminishes the effects of alkylating agents used to treat these gliomas, such as temozolomide and lomustine." (PMID 37239289, 2023). "Molecular markers such as IDH genotype, 1p/19q and O6‐methylguanine‐DNA methyltransferase (MGMT) have been widely used in glioma patients and supply valuable clinical information." (PMID 36999945, 2023). "The frequency rate of methylated MGMT promoter in glioma patients has shown discrepancies across the globe." (PMID 39760063, 2023). "In our study, verbal fluency score (SCOWA test) was an independent predictor of survival in IDH1-wt and MGMT-unmet patients with high-grade gliomas." (PMID 38168519, 2023). "MGMT overexpression contributes to TMZ resistance, whereas MGMT downregulation in glioma cells increases the tumour sensitivity to the cytotoxic effects of TMZ." (PMID 37480215, 2023). "In our hospital, the evaluation of MGMT promoter status is performed for all glioma patients when chemotherapy with temozolomide is considered." (PMID 37754483, 2023). "Transcriptional silencing of MGMT gene and increased tumor sensitivity to alkylating drugs was observed in gliomas, colorectal carcinomas, ovarian carcinomas, non-small cell lung carcinomas, head and neck carcinomas, lymphomas, etc.." (PMID 36766464, 2023). "Promoter methylation of O6-methylguanine-DNA methyltransferase (MGMT)—the major enzyme involved in repair of DNA damage induced by TMZ —serves as a useful predictor for glioma responsiveness to TMZ." (PMID 37131108, 2023). "Among these, EID3, MGMT, PMS1, and NUDT1 were significantly related to the prognosis and survival of glioma patients, and the high-risk score group had a significantly shorter survival time." (PMID 37086071, 2023). "In the TCGA-glioma dataset, risk Scores were significantly correlated with age, Grade, survival status, IDH status, MGMT status, ATRX status and BCR status." (PMID 36778644, 2023). "With regard to glioma, some studies have shown that PPIs can inhibit MGMT promoter methylation, thereby increasing the sensitivity of glioma to radiotherapy and chemotherapy." (PMID 35961680, 2023). "MGMT is also methylated to varying degrees in other glial tumors, which translates into survival benefit." (PMID 38168519, 2023). "MGMT promoter methylation, and 1p19q codeletion were other two epigenetic alterations occurred in glioma patients." (PMID 37864127, 2023). "In recent years, a number of studies showed that MRI-based radiomics can accurately predict the IDH or MGMT status of gliomas with good performance." (PMID 36900232, 2023). "Concerning the utilization of archived FFPE glioma samples for MGMT testing, the semi-quantitative MSP approach performed on FFPE samples brings about acceptable results." (PMID 36766464, 2023). "Other in vitro studies however showed that mTOR inhibition under hypoxic conditions can promote survival of glioma cell lines in vitro by reducing oxygen and glucose consumption, and promotes temozolomide resistance by increasing MGMT protein levels." (PMID 37114125, 2023). "The leading mechanism of resistance in glioma cells is the high activity of O-6-methylguanine DNA methyltransferase (MGMT), which repairs TMZ-induced DNA damage and contributes to TMZ resistance." (PMID 36675073, 2023). "The serum FAP level was found to be higher in grade 4 glioma compared to grade 3 glioma among patients with MGMT unmethylation (P = 0.2604)." (PMID 37864148, 2023). "Knowing that tumor gene status, such as IDH, O6‐methylguanine‐DNA methyltransferase (MGMT), and 1p/19q, are beneficial for treatment planning and prognosis prediction, more studies have explored the value of DL in predicting glioma gene types in recent years." (PMID 37693051, 2023).
glioma (continued). "Machine learning has also shown promise in the automated interpretation of histopathology of central nervous system tumors, identification of IDH1 mutation, MGMT promoter methylation, and 1p19q codeletion." (PMID 36836877, 2023). "Meanwhile, the different types of IDH status, 1p/19q-codeleted status and MGMT status has been proved to be crucial to clarify the subtypes of gliomas and predict the prognosis of patients." (PMID 35277559, 2022). "We studied the differences between cluster 1 and cluster 2 in pathological grade, IDH, MGMT, 1p19q, and glioma subtypes." (PMID 36159780, 2022). "Previous studies indicated that the promoter methylation of MGMT would reduced the transcription of MGMT in glioma cells, thus increasing the sensitivity to TMZ." (PMID 36118887, 2022). "Collectively, our research discovered the potential signaling mechanism associated with C3G-mediated suppression of TMZ resistance in LN-18/TR cells through miR-214-5p, which can facilitate the treatment of MGMT-induced resistance in glioma cells." (PMID 35545654, 2022). "Rescue experiments confirmed that MGMT is the downstream target of the circWDR62/miR-370-3p axis in glioma." (PMID 35817771, 2022). "Epigenetic changes are another obstacle in cancer therapy; for example, in patients with gliomas, methylation of the promoter of the DNA-repair enzyme O6-methylguanine-DNA methyltransferase (MGMT) is a problem in cancer therapy with alkylating agents." (PMID 35986321, 2022). "BMP2 increased the differentiation and apoptosis of glioma in a concentration-dependent manner through the downregulation of both MGMT and hypoxia-inducible factor-1 (HIF-1) (xref>/xref>)." (PMID 35982954, 2022). "Multivariate analysis of S100A4 expression and tumor subtype, gender, recurrence, IDH status, and MGMT status show that S100A4 is an independent prognostic factor (Multivariate Cox regression analysis p-values: all gliomas = 0.0089, GBM only = 0.0019)." (PMID 35140215, 2022). "The O6‐methylguanine‐DNA methyltransferase (MGMT) methylated glioma is more sensitive to alkylated drugs." (PMID 36134697, 2022). "DNA repair enzyme O6-methylguanine DNA methyltransferase (MGMT) is thought to be the most effective mechanism of glioma resistance to TMZ." (PMID 36249824, 2022). "The established interconnection of glycolysis with methylation of the promoter of O-6-methylguanine-DNA-methyltransferase (MGMT) of gliomas can be used to increase chemotherapy efficiency." (PMID 35625744, 2022). "One of the first and thus best-studied epigenetic modifications in the wide spectrum of neoplasia, including gliomas, is O6-methylguanine-DNA methyltransferase (MGMT) gene promoter methylation." (PMID 36361838, 2022). "We performed methylome profiling of glioma tissues (GBM WHO IV) and the primary GBM cells derived from the tissues were characterized for the mutational status of IDH1/IDH2 and methylation of MGMT as described in Materials and Methods." (PMID 35393392, 2022). "To further refine and optimize the prediction performance of GPI for glioma, we integrated GPI and clinical factors (including age, grade, IDH mutational status, 1p19q codel status, and MGMT-promoter methylation status) to construct an OS nomogram model." (PMID 35784306, 2022). "In this study, a ResNet based on radiomics features was proven to be a feasible tool for predicting the MGMT promoter methylation status of gliomas." (PMID 35743511, 2022). "In glioma patients, in fact, the expression of O6-methylguanine-DNA methyltransferase (MGMT), an enzyme involved in alkylating agent-induced DNA damage repair, is predictive of response to the treatment with carmustine and temozolomide." (PMID 39086963, 2022). "Higher expression levels of HOXC6, MMP9 and SHOX2, and lower expression levels of MYOD1 were observed in the glioma tissues with promoter-unmethylation of MGMT in TCGA." (PMID 36118887, 2022).